INS (insulin)
Diseases named in the same sentence as INS in open-access papers (continued):
Sharing a sentence is not in itself a finding about the gene and the disease.
Obesity (continued). "Furthermore, LPS receptor-deleted mice (CD14 mutants) are hypersensitive to insulin, and the development of insulin resistance, obesity, and diabetes in this animal model is delayed in response to a high-fat diet." (PMID 20706688, 2010). "In particular, the increased synthetic demand for energy availability challenges ER function, and alterations in cellular ER stress increase serine phosphorylation of IRS-1 in a JNK-dependent manner; a common finding in obesity, insulin action, and type 2 diabetes." (PMID 20936118, 2010). "11β-HSD1 knockout mice are resistant to diet induced obesity, showed improved insulin sensitivity." (PMID 20932307, 2010). "The inflammatory status related to obesity may be also originated by oxidative stress, which induces cell injury and could be able to dysregulate adipocytokine production and insulin sensitivity." (PMID 20534152, 2010). "Chavez AO showed that simple morphometric measurements of adiposity/obesity, (i.e. abdominal circumference) could explain 59% of total insulin mediated glucose uptake, and provided a feasible method to screen and identify insulin resistant in baboons." (PMID 21167068, 2010). "More recently, the intensity of the debate was fuelled by the hypothesis that HFCS lead to obesity because fructose bypasses food intake regulatory system (insulin and leptin) and favors lipogenesis." (PMID 21050460, 2010). "Interestingly emerging evidence indicates that the HO system suppresses different inflammatory events including macrophage infiltration and potentiate insulin sensitivity and glucose metabolism in obesity in a similar way as PPARγ." (PMID 20508722, 2010). "Additionally, alterations in insulin sensitivity related with obesity were coupled with alterations in inflammatory genes." (PMID 20307313, 2010). "The down-regulation of LPL in the adipose tissues, muscles and kidney under study may be due to inflammatory mediators such as tumour necrosis factor-alpha (TNF-α) which are found to be elevated in obesity and insulin resistant states." (PMID 20670429, 2010). "Central resistance to insulin and/or leptin has been proposed as important mechanisms responsible for the dysregulation of energy homeostasis, which may lead to obesity." (PMID 20796266, 2010). "Given that PPARγ is necessary for the maturation of alternatively activated macrophages, and PPARγ is a transcription factor that regulates adipogenesis, insulin sensitization and inflammation, the potentiation of PPARγ-signalling would be beneficial in obesity." (PMID 20508722, 2010). "The purpose of this study was to measure FABP4 plasma levels, assess FABP4 allelic variants, and explore potential associations with fasting glucose and insulin levels in young school-age children with and without obesity." (PMID 20156355, 2010). "Cross-sectional and prospective studies should account for potential confounders of the vitamin D-T2DM relationship, including age, ethnicity, obesity, physical activity, and diet, as well as use direct measures of adiposity, insulin sensitivity, and insulin secretion." (PMID 20011094, 2010). "However, obesity is remarkably heterogeneous as some obese patients are insulin sensitive whereas others are insulin resistant." (PMID 20846382, 2010). "Circulating ghrelin levels are correlated with obesity, and insulin may be an important regulator of plasma ghrelin levels in different states of nutrition." (PMID 20920174, 2010). "The potential utility of liver fat percent measured by MRS is highlighted by the finding of patients with 'metabolically-benign' obesity; i.e. obese patients with normal insulin sensitivity and lower liver fat percentages compared to insulin-resistant obese individuals." (PMID 20553596, 2010). "Thus, in Eps8KO mice, reduced bodyweight both during aging- and diet- induced obesity correlates with improved insulin sensitivity." (PMID 20209148, 2010).
Obesity (continued). "BW gain is probably a benefit in purely insulin-deficient patients in whom lack of insulin is responsible for lean tissue loss, but in T2D the worsening of existing obesity seems undesirable." (PMID 20721344, 2010). "On the other hand, high fiber diets might protect against obesity and CVDs by lowering insulin levels." (PMID 19166627, 2009). "Since progressive obesity in LY mice is accompanied by the development of insulin and leptin resistance, changes in gene expression may be related to altered metabolic state." (PMID 19650929, 2009). "Obesity and T2DM has been associated with tissue lipid accumulation and such ectopic TAG accumulation, also known as tissue steatosis, is implicated in the impairment of insulin signaling." (PMID 19638239, 2009). "We therefore hypothesize that miR-134 plays a role in adipocyte differentiation and may contribute to the either hypertrophic insulin resistant or hyperplastic insulin sensitive subtype of obesity." (PMID 19259271, 2009). "An emerging hypothesis is that metabolic aberrations accompanying obesity lead to changes in hormones and cytokines, including insulin." (PMID 19190630, 2009). "Adiponectin activity is commonly reduced in human obesity, thus affecting insulin sensitivity." (PMID 19606226, 2009). "Aging LY mice become insulin-resistant and hyperleptinemic with increasing obesity." (PMID 19650929, 2009). "Thus, obesity should be prevented by reducing insulin secretion in those cases with hypothalamic involvement." (PMID 19341477, 2009). "Modulation of ovarian gene expression may involve altered insulin and/or leptin exposure or sensitivity, which is closely related to progressive obesity." (PMID 19650929, 2009). "This may be of considerable physiological importance, since glucose has been proposed as a potential mediator of beta cell hyperplasia in insulin resistant states such as obesity and pregnancy." (PMID 19343226, 2009). "Individuals with PWS and obesity may have insulin insensitivity, but it is less pronounced than in subjects with simple obesity." (PMID 18320030, 2008). "The inhibition of 11β-HSDl indicates that LXR might be involved in suppressing glucocorticoid effects, which might lead to reduce development of obesity and improved insulin sensitivity." (PMID 20046702, 2008). "WRN polymorphisms may also have relevant clinical significance for "normal states" such as stress, obesity, aging or acute inflammation, because they are characterized by high levels of insulin, TNFα, TGFβ." (PMID 18312663, 2008). "In addition to increased insulin sensitivity and glucose tolerance, anti-obesity effects such as reduced food intake, body weight gain and reduced percentage body fat have been reported." (PMID 18269730, 2008). "Moreover, the PUFA from the fish, DHA and EPA exhibit "anti-obesity" effect as well as improving insulin sensitivity." (PMID 18950537, 2008). "Also, QTLs for the BP factor (LOD of 3.2 on chromosome 15q15), for the lipids-INS factor (a LOD of 3.08 on chromosome 8p23), and for the obesity-INS factor (LOD of 3.1 on chromosome 3p26) were reported in whites." (PMID 19038053, 2008). "Of the circulating factors increased in obesity – including leptin, insulin, NEFAs and TGs – only the latter two are raised by short-term high-energy feeding (prior to obesity onset), suggesting they may play the more critical role." (PMID 17570846, 2007). "This may represent an adaptation of the skeletal muscle in response to the chronic overload imposed by obesity and/or the metabolic alterations (resistance to insulin and altered metabolism of fatty acids) imposed by excess weight." (PMID 17992391, 2007). "It is still unclear whether individuals with the same degree of obesity but different weight histories since young adulthood have different insulin concentration, prevalence of metabolic syndrome components and their clustering." (PMID 17827860, 2007).
Obesity (continued). "It is also paradoxical that the TZD's increase insulin sensitivity but also pre-dispose to obesity." (PMID 17663761, 2007). "Also, deletion of S6K1 in mice renders them resistant to age- and high-fat diet-induced obesity while enhancing insulin sensitivity." (PMID 16404421, 2006). "Results support the hypothesis that MetS is a compound phenotype, where obesity and its relationship to lipids and insulin are clearly the driving force of MetS." (PMID 15656912, 2005). "As circulating levels increase, leptin acts to modulate food intake, but in obesity, its rise with increasing body fat has limited effect on satiety, suggesting negative regulators of leptin and insulin signalling, such as leptin receptor and adiponectin, are present." (PMID 16160698, 2005). "INS contributed in two important factors (obesity and lipids)." (PMID 16076393, 2005). "However, in all data in Whites, the first factor represented a stronger mixture of central obesity, obesity and INS, leaving the fourth factor with mainly WHR loading." (PMID 15656912, 2005). "Obesity and its relationship to lipids and insulin is clearly the dominant factor in MetS." (PMID 15656912, 2005). "The fact that adiponectin is secreted initially by fat but levels are reduced as fat depots increase, may help resolve the paradox of both lipodystrophy and obesity both being insulin-resistant states." (PMID 15530168, 2004). "This randomized, repeated-measures study examined whether substituting refined wheat or corn flour with soy flour influences postprandial glucose and insulin plasma concentrations, appetite ratings, and product acceptability in adults with overweight or obesity." (PMID 42074986, 2026). "Furthermore, the co-existence of obesity and poor nutrition forms a "syndemic," where shared pathological pathways including chronic inflammation, insulin resistance, and oxidative stress may synergistically impair neurocognitive recovery." (PMID 41543809, 2026). "Building on this foundation, an examination of the molecular mechanisms of LRRC8A in adipocyte differentiation, lipid metabolism, and insulin sensitivity could provide complementary insights and potentially identify therapeutic strategies for addressing the global obesity epidemic." (PMID 41439137, 2026). "For example, populations with higher prevalence of metabolic syndrome or obesity (USA) may demonstrate enhanced insulin signaling, while subjects of African genetic heritage (RSA) may preferentially express proliferative and translational machinery activation 48-50." (PMID 41584049, 2026). "Thus, the study shows that obesity promotes hepatic DNL in the insulin-resistant state via Vimentin, a hitherto unknown organokine." (PMID 42320628, 2026). "Moreover, growth hormones and insulin are amplified by obesity and may partly explain the significant positive relationships of SBP and DBP with BMI in 2012 and 2013, but not in 2014 when height plateaued during the end of adolescence in our population." (PMID 40989822, 2025). "In contrast, sometimes women with higher pre-pregnancy BMI may consciously restrict food intake due to advice or personal concerns about obesity-related risks, and they may also experience metabolic resistance to weight gain due to insulin resistance and altered lipid metabolism." (PMID 41302196, 2025). "Obesity-associated declines in glycine and serine compromise antioxidant capacity, whereas MBS may restore their concentrations, thereby improving redox balance and insulin sensitivity." (PMID 40710534, 2025). "Research findings indicate that the link between visceral adipose tissue and cancer risk may involve systemic mechanisms, such as leptin, glucose, insulin, and inflammatory cytokines, which are systemic markers of obesity-related adipose tissue inflammation and may promote tumor development." (PMID 40007994, 2025).
Obesity (continued). "To investigate the mediators of interorgan communication, we monitored the blood glucose, serum insulin, serum leptin, and plasma GLP-1 levels in 20-week-old mice, because prolonged increases of these metabolites are known to be associated with the development of obesity." (PMID 40179260, 2025). "Furthermore, obesity is not only characterized by abnormal weight gain but is more critically defined by excessive adipose tissue accumulation, dyslipidemia, impaired glucose tolerance, and elevated fasting insulin levels." (PMID 40362407, 2025). "In a retrospective study of 51 T1D people with obesity, tirzepatide was associated with 8.5% mean Weight loss, 0.9% HbA1c reduction, and a 31.6% decrease in daily insulin dose over 8 months, with no increase in hypoglycemia; GI symptoms were the main side effect; overall tolerability was high." (PMID 41212412, 2025). "Intriguingly, Postn deficiency has been reported to attenuate LPS-/HFD-induced AT fibrosis and to improve IR; thus, the lower Postn levels found herein may contribute to healthy hyperplastic AT expansion and maintain insulin sensitivity during obesity, as we observed in the LFABP−/− mouse model." (PMID 40497936, 2025). "Adipocytokines such as leptin and adiponectin, which regulate and affect insulin sensitivity and signaling, are deregulated in both psoriasis and obesity, and plasma levels of adiponectin, which has anti-inflammatory action, are decreased in obesity, psoriasis, IR, and T2D." (PMID 40806666, 2025). "Additionally, several pathways associated with metabolic diseases, such as amino acid and fatty acid metabolism, insulin signaling pathways, and obesity-related pathways, may also influence subcutaneous and intramuscular fat deposition and metabolism." (PMID 40149398, 2025). "Surprisingly, laminitis reported in this study was not linked to obesity but associated with insulin levels <20 mU/L, lower body weight, and glucose levels, along with higher concentrations of albumin, catalase, glucose, insulin, and IGF-1 compared to obese mares." (PMID 40901060, 2025). "The likely explanation for this relation could be indicated by the evidences in which obesity increases the secretion of insulin resistant non esterified fatty acids (NEFAs) from adipose tissue and consequently results in decreased insulin sensitivity, which in turn is a risk factors of T2DM." (PMID 40168266, 2025). "This suggests the potential for FFAR4 activation to extend from monocytes to resident adipose tissue macrophages, which could have implications in promoting pro-resolving mechanisms and improving insulin sensitivity, thereby modulating the inflammatory response in obesity." (PMID 41373925, 2025). "African American (AA) women are disproportionately burdened by obesity, with a higher prevalence compared to European Americans (55% vs. 38%), which has been attributed in part to a metabolic profile characterized by lower insulin sensitivity (SI) and higher acute insulin response to glucose (AIRg)." (PMID 40931394, 2025). "Indeed, Megamonas is the most markedly elevated genus in obesity, and obese individuals carrying Megamonas show higher body mass index, body weight, waist circumference, hip circumference, 2-h postprandial glucose, and 2-h postprandial plasma insulin levels." (PMID 40979562, 2025). "Additionally, randomized controlled trials evaluating interventions aimed at improving insulin sensitivity and reducing obesity could inform targeted prevention strategies for stroke." (PMID 40417114, 2025). "Similarly, studies in pediatric patients with obesity showed a significant decrease in BMI by 2.26, BMI z-score by 0.31, waist circumference (−5.07 cm), and insulin level (−5.41 μU/mL) when treated with sodium butyrate for 6 months, compared with the placebo-treated group." (PMID 40305160, 2025).
Obesity (continued). "Moreover, VCO exhibits antidiabetic, anti-obesity, and antiasthmatic properties by enhancing insulin secretion, and inhibiting fat accumulation, alongside potent antimicrobial activity against diverse pathogens, including bacteria, viruses, fungi, and protozoa." (PMID 40863333, 2025). "All these coordinated changes (all data included from the study) in gene and protein expression in one of the insulin-sensitive tissues; adipose tissue may partially provide a molecular mechanism for the fat mass deposition during obesity and how that would be overcome by L-Arg supplementation." (PMID 40764680, 2025). "Notably, elevated blood levels of BCFAs may corelate negatively with biomarkers of obesity, insulin sensitivity, and inflammation, suggesting a positive effect of BCFAs on energy metabolism in the body." (PMID 40427489, 2025). "Smaller adipocytes are thought to be more insulin-sensitive; thus, the effect of Lfabp ablation on the quality of sWAT may contribute to the previously reported MHO phenotype of the LFABP−/− mouse, which is characterized by normal plasma glucose and insulin levels despite marked obesity." (PMID 40497936, 2025). "According to the observation, an excessive generation of free fatty acids in our cohort could pose an increased severity to coronary atherosclerosis, especially among those who are comorbid with T2DM, and obesity, by inducing endothelial dysfunctions and defects in insulin signaling and sensitivity." (PMID 41244768, 2025). "Notably, C57BL/6J mice that are maintained on an HFD develop obesity as glucose tolerance is impaired and insulin resistance results in elevated blood glucose and insulin levels." (PMID 40149720, 2025). "Additionally, prolonged obesity may impair insulin secretion and increase resistance to glucose uptake." (PMID 39663299, 2025). "In individuals with obesity, alterations in lipolysis, fatty acid delivery to skeletal muscle, insulin and catecholamine responses, as well as impairments in mitochondrial transport and oxidation, may shift the Fatmax intensity or reduce MFO due to specific metabolic restrictions." (PMID 41590220, 2025). "Considering the factors that may influence insulin response in obesity, such as efficiency of insulin clearance by hepatocytes and functionality of peripheral vessels, we further compared the circulating c-peptide levels during intravenous glucose tests on CD- and WD-fed mice." (PMID 40488531, 2025). "Moreover, while both HF and high-sugar diets promote visceral fat accumulation and obesity, they might induce insulin resistance via distinct mechanisms that extend beyond the effects of obesity alone." (PMID 40573161, 2025). "In obesity, adipose tissue undergoes morphological and endocrine remodeling, triggering low-grade inflammation (including neutrophil activation, macrophage polarization towards a pro-inflammatory phenotype, and the production of pro-inflammatory cytokines), insulin resistance, and organ dysfunction." (PMID 41305664, 2025). "Firstly, we did not measure fasting blood glucose and insulin sensitivity after the 16-week HFD feeding (used to establish the obesity model) because required fasting procedure could cause significant body weight fluctuations in mice." (PMID 41228499, 2025). "The greater decline in HOMA-B among patients with obesity is consistent with previous studies, suggesting that elevated HOMA-B at baseline may reflect compensatory hyperinsulinemia that diminishes as insulin sensitivity improves with weight loss through lifestyle intervention." (PMID 40843316, 2025). "However, to our knowledge, no data exist on the effect of obesity on brain inflammation and its association with insulin‐stimulated BGU in humans." (PMID 40926735, 2025). "Thus, obesity creates an “insulin-resistant” gene signature in mammary without gross loss of PRL receptor, implicating downstream or cross-talk inhibition of STAT5." (PMID 40868103, 2025).